INS (insulin)
Diseases named in the same sentence as INS in open-access papers (continued):
Sharing a sentence is not in itself a finding about the gene and the disease.
Insulin resistance (continued). "DAGs are postulated to be mediators of insulin resistance, providing a link between increased lipid and reduced insulin-stimulated glucose uptake." (PMID 36394259, 2022). "In contrast, excess fat intake led to a delayed glucose clearance in glucose tolerance testing, higher plasma insulin concentrations, an increased insulin resistance and a diminished insulin sensitivity indicating a prediabetic state in HFD-fed mice." (PMID 36297003, 2022). "Insulin resistance will increase the level of ROS, which will further damage the metabolic and vascular factors in the insulin signal transduction pathway." (PMID 35236828, 2022). "Leptin’s role in enhancing insulin sensitivity and improving insulin resistance in lipodystrophy and diabetic models has also been reported." (PMID 34996484, 2022). "The characteristic attenuated effect of insulin in peripheral tissues, indicative of insulin resistance, precedes the development of hyperglycemia." (PMID 35883605, 2022). "Insulin resistance leads to increasing insulin secretion, leading to beta-cell exhaustion or burnout." (PMID 35163806, 2022). "Insulin resistance and insufficient pancreatic beta cell insulin secretion are the mainly characteristics of type 2 diabetes." (PMID 34976192, 2022). "The glucose tolerance test (GTT) and insulin tolerance test (ITT) results indicated that ablation of ASC impaired glucose tolerance and insulin sensitivity, resulting in insulin resistance." (PMID 36077447, 2022). "Several cross-sectional studies have shown that CRP levels are associated with obesity, increased fasting blood sugar levels, and impaired insulin sensitivity, all components of insulin resistance." (PMID 35883605, 2022). "Compared to the other phenotypes, isolated IGT was strongly associated with family history of T2DM and showed the worst metabolic profile in terms of insulin resistance, low insulin sensitivity, low DI and atherogenic lipid profile." (PMID 35579861, 2022). "A previous study showed that disruption of insulin secretion by pancreatic beta cells generally occurs because of insulin resistance in skeletal muscle, liver, and adipose tissues." (PMID 35846491, 2022). "Blood samples were taken before and after 28 days of treatment for fasting plasma glucose (FPG) and insulin analysis, which were used for a Homeostatic Model Assessment for Insulin Resistance (HOMA-IR) calculation." (PMID 35846491, 2022). "Tzeng and co-authors demonstrated a double effect of kaempferitrin, reporting that it improves insulin resistance by activating the classic insulin transduction pathway and increasing adiponectin secretion." (PMID 36145266, 2022). "Dynamic changes in serum GIP, GLP-1, insulin, and insulin resistance between 1 and 4 weeks after PBM, measured using HOMA-IR, were identified for the evaluation of underlying mechanisms on altered gut microbiome over 1–4 weeks in the D-LED PBM group." (PMID 36359885, 2022). "But in insulin resistance, insulin receptors become resistant to insulin which ceases this mechanism, and insulin and glucose levels elevate in the bloodstream." (PMID 36324618, 2022). "Impaired insulin signaling is compensated for the overproduction and secretion of pancreatic insulin, thus driving to insulin resistance, commonly seen in obese patients." (PMID 36403025, 2022). "Insulin resistance occurs when normal concentrations of insulin fail to achieve an appropriate biological response downstream of the insulin receptor." (PMID 36465627, 2022). "The pathophysiology of T2D is characterized by insulin resistance and a reduction in insulin secretion, with the latter playing important roles in both the onset and progression of the disease." (PMID 35563495, 2022). "Regarding reported metabolic outcomes, fasting blood glucose was statistically reduced in two studies, yet increased in another, whilst fasting insulin and the Homeostatic Model Assessment for Insulin Resistance (HOMA-IR) index were improved in one study." (PMID 36278523, 2022).
Insulin resistance (continued). "Male and female p20 rats present physiological insulin resistance with differences in the protein activation of insulin signaling." (PMID 36224569, 2022). "Thiazolidinediones (TZDs) are insulin sensitizers that primarily reduce insulin resistance in insulin-sensitive tissues in the periphery." (PMID 35406040, 2022). "We selected two indicators directly related to insulin resistance and obesity, namely, the fasting insulin level and BMI, to evaluate the efficacy of acupuncture and moxibustion for treating metabolic disorders, and both methods showed a positive result." (PMID 35399633, 2022). "Compared to the controls, PCOS rats showed a statistically significant higher serum fasting glucose and insulin levels, as well as a higher Homeostatic Model Assessment Index of insulin resistance (HOMA-IR)." (PMID 35845946, 2022). "Supporting this possibility, in the rat, blocking endothelin action prevents insulin’s vasoconstrictive effect on muscle microvasculature during free fatty acid-induced insulin resistance." (PMID 34957859, 2022). "Insulin signalling is disturbed at multiple levels during insulin resistance, resulting in decreased glucose absorption in insulin-sensitive peripheral tissues, according to our earlier findings on the liver and peripheral organs." (PMID 35268696, 2022). "The coexistence of insulin secretory defects and insulin resistance can raise maternal blood glucose levels, resulting in adverse pregnancy outcomes." (PMID 34996380, 2022). "During insulin resistance, nitric oxide (NO) production is impaired while the supportive effect of insulin on calcium ion influx and vasoconstriction is still present." (PMID 35406053, 2022). "In the human liver, leptin has been shown to attenuate the number of insulin-induced actions that ultimately lead to insulin resistance." (PMID 36005598, 2022). "Experiments in obese mice showed both a reduction in macroautophagy-related genes (atg 5 and atg 7), and the in vivo downregulation of these genes (particularly atg 7) lead to insulin resistance and a reduction of insulin secretion in β cells." (PMID 35326371, 2022). "Insulin resistance (IR) refers to a decreased tissue response to insulin stimulation, which can lead to failure to maintain glucose homeostasis, type 2 diabetes (T2DM), and metabolic syndrome." (PMID 35677718, 2022). "This is owing to the different roles of insulin in different people, since it induces glucose to influx into tissues, and these tissues have a decreased responsiveness to insulin activity in insulin resistance." (PMID 36128550, 2022). "Many epidemiological investigations have demonstrated that plasma PFOS concentrations are positively correlated with elevated insulin levels, augmented pancreatic β-cell activity, and insulin resistance in adults as well as in overweight children." (PMID 35457000, 2022). "The most common direct measure of insulin resistance is the high insulin/ normoglycaemic clamp (HEC) technique, which is invasive, complex and impractical." (PMID 36211651, 2022). "There is emerging evidence that link microRNAs as mediators of metabolic diseases including obesity and insulin resistance, as these can regulate multiple cellular pathways such as insulin signaling and adipogenesis." (PMID 35455702, 2022). "Adipose tissue has been identified as a source of sST2 and the induction of sST2 in a mouse model led to higher insulin secretion and exacerbated adipose tissue inflammation and insulin resistance." (PMID 35277168, 2022). "A study of weight loss and changes in insulin resistance and serum MBL levels showed that weight loss-induced changes in serum MBL concentration were positively associated with the increase in insulin sensitivity." (PMID 36618347, 2022). "Insulin resistance is a condition in which insulin action is lower than normal at physiological insulin concentrations." (PMID 36145191, 2022).
Insulin resistance (continued). "In T2DM, chronic insulin resistance and a progressive decline in β-cell function result in β-cell dysfunction and defect in insulin secretion." (PMID 36232291, 2022). "IRS1 plays critical roles not only in the transduction of insulin signals but also in the development of insulin resistance." (PMID 35790738, 2022). "Studies have suggested an effect of the THADA gene on insulin secretion and insulin resistance, as well as an effect on body mass index." (PMID 36672824, 2022). "First, T2DM is characterized by normal glucose tolerance followed by insulin resistance, resulting in a compensatory increase in insulin secretion, and deterioration of carbohydrate metabolism." (PMID 35203115, 2022). "In contrast, in the presence of insulin resistance in the body, insulin sensitivity decreases and dephosphorylated GSK-3β increases, resulting in reduced glycogen synthesis and increased blood glucose." (PMID 35845577, 2022). "This is alarming as free fatty acids and adipokines can impair insulin sensitivity and bring about the cascade of insulin resistance, hyperinsulinemia, and T2D." (PMID 35812257, 2022). "Consistent with dispersal being an important physiological mechanism, we observed that insulin-stimulated GLUT4 dispersal is reduced under conditions of insulin resistance." (PMID 36446811, 2022). "Baseline data from bariatric surgery patients with Class III obesity showed that those with insulin resistance had a higher REE than those who were insulin-sensitive, even when adjusted for fat-free mass." (PMID 36501139, 2022). "These include, for example, a progressive increase in insulin resistance in the second and third trimesters and upregulation of pancreatic insulin secretion." (PMID 36432486, 2022). "A meta-analysis of 22 randomized trials demonstrated that dietary fiber is negatively correlated with fasting insulin and the homeostatic model for insulin resistance values, while it can significantly decrease HbA1c and fasting glucose." (PMID 36432488, 2022). "It's a carbohydrate, lipid, and protein metabolism condition characterized by insulin secretion insufficiency(relative or total) and different degrees of insulin resistance." (PMID 37693075, 2022). "Like insulin, amylin levels are higher than normal in patients with obesity or insulin resistance, while the coexistence of hyperinsulinemia and hyperamylinemia is common." (PMID 35269827, 2022). "In young women with PCOS, hyperandrogenism, menses irregularities, and insulin resistance represent the pathophysiological role of excess androgen and insulin in PCOS." (PMID 36340665, 2022). "Another study among US adults found similar results, with increased use of cannabis within the last month resulting in lower levels of fasting insulin and insulin resistance, while also producing a smaller waist circumference." (PMID 35328862, 2022). "Insulin resistance can improve carcinogenesis by direct insulin/insulin receptor pathway and indirect IGF signaling pathway." (PMID 36003786, 2022). "Regarding insulin resistance markers, there was a prevalence of 12.2% (95% CI; 11.1, 13.5) in undesirable insulin, 24.7% (95% CI; 22.8, 26.7) in high HOMA-IR, and 4.6% (95% CI; 3.8, 5.4) in undesirable blood glucose." (PMID 36078265, 2022). "This ectopic lipid accumulation promotes insulin resistance by inhibiting insulin-induced GLUT4 glucose transporter trafficking and glucose uptake." (PMID 35954283, 2022). "Regarding insulin resistance, fasting, postprandial insulin, and c-peptide significantly decreased, while HOMA-IR improved with trends toward significance (p = 0.072) from 5.5 ± 5.19 to 4.3 ± 3.16." (PMID 35242882, 2022). "Animal models of insulin resistance have been used to demonstrate improved insulin sensitivity and reduced glucose elevation with blueberry supplementation." (PMID 35458181, 2022).
Insulin resistance (continued). "Insulin resistance (IR), reflecting the insensitivity state of the peripheral tissue toward insulin, leads to defective glucose uptake, decreased glycogenesis and dyslipidemia." (PMID 36684574, 2022). "T2DM is characterized by decreased insulin sensitivity of tissues (especially skeletal muscles and liver) with concomitant insulin resistance and impaired insulin secretion by the β-cells of the Langerhans islets in the pancreas." (PMID 35885378, 2022). "One consequence of increased insulin resistance is a compensatory increased insulin secretion by pancreatic beta cells, which contributes to beta cell dysfunction and advanced senescence at a younger biological age than other ethnic groups." (PMID 35444916, 2022). "Gyps can significantly reduce FINS, FBG, and HOMA-IR in HFD-induced NASH, suggesting that Gyps can increase insulin sensitivity and improve insulin resistance." (PMID 36091227, 2022). "GPR84 has been demonstrated to be involved in the regulation of energy metabolism mediated by the secretion of insulin and inflammatory responses related to insulin resistance." (PMID 36368953, 2022). "T1DM is caused by autoimmune destruction of insulin-producing pancreatic β cells, while T2DM is primarily mediated by peripheral insulin resistance." (PMID 36383675, 2022). "PI3K/AKT signaling pathways can effectively improve insulin sensitivity, relieve insulin resistance, and regulate glucose metabolism." (PMID 35701780, 2022). "Insulin resistance in pregnancy is the failure of a precise concentration of insulin to affect an anticipated biological response of nutrient metabolism caused by increased maternal adiposity and insulin-desensitizing influences of placental hormones." (PMID 35794524, 2022). "Several studies have shown that non-insulin-based indices of insulin resistance are a valid surrogate for the early identification of insulin resistance." (PMID 36613109, 2022). "When the number of pro-inflammatory M1 ATMs is increased in obesity, TNF-α and IL-6 are highly secreted, which are involved in the insulin resistance of adipocytes by inhibiting insulin signaling and stimulating lipolysis of adipocytes." (PMID 36499655, 2022). "HBP contributes to insulin resistance mainly through the increased O-GlcNAc modification of insulin-signaling-pathway intermediates, which can be reversed with GFAT inhibitor treatment." (PMID 36005597, 2022). "Adipose tissue insulin resistance leads to sustained lipolysis, which increases circulating fatty acid and ultimately impairs whole-body insulin signaling." (PMID 36559697, 2022). "Serum testosterone concentrations decline when insulin resistance is treated with metformin or insulin levels are reduced with diazoxide." (PMID 36140452, 2022). "These favor insulin resistance, which refers to the inability of the adipose cell to respond to insulin due to the blocking of enzymes and molecules participating in the insulin signaling cascade." (PMID 36235241, 2022). "At baseline, patients in the LMO group also showed severe hepatic insulin resistance but decompensated insulin secretion, which resulted in significantly decreased DI and increased HbA1c." (PMID 36407309, 2022). "MicroRNAs have been implicated as mediators of metabolic diseases including obesity and insulin resistance, as these can regulate multiple cellular pathways such as insulin signaling and adipogenesis." (PMID 35455702, 2022). "Insulin resistance is defined as a state in which more than normal amount of insulin is required to elicit a response." (PMID 37361870, 2022). "In type 2 DM and hepatogenous DM, insulin resistance is common, and the insulin level increases, boosting the formation of oxygen free radicals and stimulating the release of inflammatory mediators including tumor necrosis factor-α (TNF-α)." (PMID 35345832, 2022). "Insulin resistance and impaired insulin signalling in the CNS have detrimental effects on critical brain function and promote neurodegenerative processes." (PMID 36555450, 2022).
Insulin resistance (continued). "Then, it will land in the present to analyze the insulin role on mitochondrial health and the effects on insulin resistance and neurodegenerative diseases that are IR-dependent." (PMID 35741464, 2022). "Fatty acids have been reported to improve insulin resistance and to play an important role in glucose/insulin metabolism." (PMID 36618687, 2022). "The dysregulation of Ca2+ homeostasis is related to metabolic diseases such as obesity, insulin resistance, and T2D, and the intracellular Ca2+ levels are important for optimal insulin signaling in skeletal muscle." (PMID 36358481, 2022). "Evidence indicates that serine phosphorylation of IRS-1 leads to impaired insulin signaling and contributes to insulin resistance." (PMID 35011728, 2022). "Insulin resistance is a metabolic disorder and it is defined as the inability of a known quantity of insulin (exogenous or endogenous) to increase glucose uptake and utilization in an individual as much as it does in the healthy population." (PMID 36613051, 2022). "In contrast, insulin resistance is characterized by poor vascular NO synthesis and reduced insulin-induced vasodilation, as well as a reduction in basal NO production." (PMID 36157467, 2022). "Insulin resistance was defined as failure of insulin to lower blood glucose levels by 40% within 60 min in 6-hour-fasted mice." (PMID 35058456, 2022). "Since association between stress and insulin resistance has not been extensively studied, the aim of the current review was to present the possible molecular interactions by which stress can impair insulin signaling and induce insulin resistance." (PMID 35368460, 2022). "As expected, insulin resistance treatment diminished the insulin-stimulated GLUT4-myc signal, denoting reduced GLUT4 translocation/PM integration, relative to control cells (bar 4 vs. bar 2)." (PMID 35222279, 2022). "Since interventions that improve IR are organ specific, it is vital to estimate which organs are resistant to insulin, as well as the level of insulin resistance in each organ." (PMID 35885586, 2022). "Abnormalities in insulin secretion due to the destruction of β-cells or damaged pancreas or insulin resistance reduce the level of insulin in the blood and hamper the glucose intake in cells." (PMID 35795141, 2022). "OB people also had lower IGF1 (P < 0.05), and 25OHD (P < 0.001) and higher PTH (P < 0.05), insulin, glucose, homeostatic model assessment for insulin resistance (HOMA-IR) (all P < 0.001) than NW people." (PMID 36173650, 2022). "Low SgIo is associated with higher fasting insulin levels and HOMA-R, suggesting reduced Sg in the presence of hepatic insulin resistance." (PMID 36355105, 2022). "Insulin resistance was significantly higher whereas insulin levels were reduced in the diabetic mice compared to control group." (PMID 35242140, 2022). "(2012) reported that postmenopausal women with T2DM who took flavan-3-ols and isoflavones for a year exhibited significant reductions in estimated peripheral insulin resistance and persistent improvements in lipid profile and insulin sensitivity." (PMID 36440220, 2022). "In mice fed with a high-fat diet, Angptl4 overexpression alleviated glucose intolerance and insulin resistance by promoting insulin signaling via IRS-1 phosphorylation." (PMID 36292250, 2022). "Insulin resistance is the early stage of type 2 diabetes, when high glucose blood levels lead to an increase in pancreatic insulin production, which results in increased glucose output and lipogenesis via the liver." (PMID 36014755, 2022). "This review will summarize the research progress on the mechanisms of R4 RGS subfamily proteins in insulin secretion and insulin resistance and analyze their potential value in the treatment of T2DM." (PMID 36497154, 2022).